TNF (tumor necrosis factor)
Diseases named in the same sentence as TNF in open-access papers (continued):
Sharing a sentence is not in itself a finding about the gene and the disease.
infection (continued). "Because these biological agents act earlier in the immune response chain, in comparison to the TNF-α blockers, they are potentially more immunosuppressive and thus infection is a concern." (PMID 20606887, 2010). "Appropriate levels of TNFα are necessary for homeostatic functions like protection from infection, haematopoiesis, immune response regulation, cellular growth in wound healing, tumor regression and immune surveillance." (PMID 20463923, 2010). "Although typical pro-inflammatory/microbicidal mediators TNF-α and iNOS remained at basal levels following infection in both wt and KO mice, IL-12p40 levels were reduced in LXRα KO mice." (PMID 21103366, 2010). "Infection of macrophages with Mtb-Δeis increased the production of tumor necrosis factor-α and interleukin-6 over the levels produced by infection with wild-type or complemented strains." (PMID 21187903, 2010). "Infection of macrophages with either the katG mutant or the nuoG deletion mutant of Mtb increased the amount of secreted TNF-α." (PMID 20421951, 2010). "After 3 h of infection, cells were washed, induced with TNFα, and at 15, 45, 60, and 75 min post TNFα-induction, the cells were fixed, stained with Hoechst 33342, and analyzed by automated microscopy." (PMID 20126447, 2010). "In the present study, TJA infection appears as a rare but potentially severe complication of TNFα blockers." (PMID 20637100, 2010). "Mice treated with IL-1β depleting antibodies were not significantly more sensitive to CO92ΔyopH infection than the control mice and only 10% of the mice treated with the TNF-α depleting antibodies succumbed to infection." (PMID 20565713, 2010). "In comparison, an intranasal infection with C. muridarum induced a T cell response that consisted predominantly of TNFα/IFN-γ co-expressing effector CD4+ T cells and an antibody response consisting of C. muridarum specific IgG1, IgG2a but also IgA." (PMID 20505822, 2010). "A549 exhibited damped oscillations after infection with H. pylori, but stable translocation after stimulation with TNFα or IL-1β." (PMID 20233427, 2010). "The resolution of inflammation was delayed in mice challenged with the first isolate and the message for IFN-γ and TNF-α in the spleen was lower within the first few hours post-infection." (PMID 20405013, 2010). "As expected, individuals with symptomatic infection (mild or severe) presented higher levels of both TNF-alpha and SOD-1 than those who were symptomless." (PMID 20386593, 2010). "In particular, we examined levels of IL-8 and TNFα, which are among the first cytokines to be secreted by macrophages particularly upon infection with certain viruses." (PMID 20596538, 2010). "It is important to inhibit apoptosis from the extrinsic pathway since many in vivo stimuli are present during infection such as TNF-α and Fas ligand." (PMID 20429941, 2010). "In conclusion, these results serendipitously reveal a novel connection between NOX2 activity, phagosomal ROS, and TNF-α signaling during infection-induced apoptosis in macrophages." (PMID 20421951, 2010). "After 24 h, OppD-KO infection led to lesser amounts of TNF-α, IL-1β and IL-6 production in macrophages compared to the wild type." (PMID 20808924, 2010). "In this study, we observed that although coinfected animals presented high levels of serum TNF-α during the acute phase of infection, the potential toxic effects of TNF-α were counterbalanced by the production of significant serum levels of IL-10." (PMID 20967289, 2010). "Consistently, infection of mice for 24 h with Ye resulted in the increased production of the proinflammatory cytokines IL-12 and TNF by CD4+ and CD4−CD8α− DCs compared to PBS-treated mice." (PMID 21124820, 2010). "At 3 hours post-H5N1/2004 infection, there were 2-5 folds increase in the expression of TNF-α and CCL-5/RANTES." (PMID 21108843, 2010).
infection (continued). "As part of the innate immune response during infection, a number of cytokines such as tumor necrosis factor alpha (TNF alpha) and other immune factors, are produced and act on the reproductive system." (PMID 20385004, 2010). "By 48 h post-infection the levels of both cytokines had decreased but remained significant with concentrations of TNF-α = 45 ± 12 pg/ml, and IL-1β = 104 ± 12 pg/ml." (PMID 20565713, 2010). "Accordingly, hMDM infected with r-BCG PGL-1 produced lower amounts of the inflammatory cytokine TNF-α than BCG-infected controls after 2 hours of infection, even though bacteria expressing PGL-1 were more efficiently internalized than the WT controls." (PMID 20975946, 2010). "Twenty-two cases of TJA infection in patients treated with TNFα blockers were collected: 13 from the RATIO registry and 9 through the websites of the French Societies of Infectious Diseases and of the Club Rheumatism and Inflammation." (PMID 20637100, 2010). "TNF-alpha, IL-6 and IL-10 expression was also modulated upon infection showing a TLR2-specific dependent IL-10 secretion." (PMID 20523725, 2010). "After i.p. infection with L. monocytogenes Ly6Clow monocytes rapidly extravasate into the peritoneum, induce an early inflammatory response by secretion of TNF, and activate genes involved in macrophage differentiation." (PMID 21179567, 2010). "Using TAPI-2, an inhibitor of the metalloproteases that cleave CD62L and TNFα, we were able to perform intracellular cytokine staining on memory T cells at day 60 post-infection whilst maintaining expression of CD62L." (PMID 21124875, 2010). "After infection, the TNF-α secretion which correlates to the IFN-γ secretion (p<0.0001) also showed the highest values in the F3sap and F1sap vaccinated individuals (447.44 pg/ml and 431.40 pg/ml, respectively, not shown)." (PMID 21085470, 2010). "Higher levels of IL-12, IFN-γ and TNF-α, cytokines that correlate with resistance to the infection, have been produced by spleen cells from infected females, in response to paracoccin stimulus." (PMID 20505765, 2010). "This is characterized by the recruitment of highly activated T-lymphocytes and macrophages to the lungs, and expression of IFNγ, TNF, cytokine and chemokine signaling pathways, four weeks post-infection." (PMID 20824205, 2010). "Early cytokines like TNF and IL-1 peak within the first hours after the infection, then circulatory levels revert to near baseline by 3-4 hours." (PMID 20628562, 2010). "Several candidate genes were checked, one of which was TNF-α because of its robust role in initial response to infection influences both innate and acquired immunity." (PMID 20420684, 2010). "As expected, the presence of the control antibody did not affect the difference observed between WT BCG and r-BCG PGL-1: infection of hMDM with r-BCG PGL-1 resulted in defective TNF-α production, compared to hMDM infected with WT BCG." (PMID 20975946, 2010). "Neutralization of TNF-α also significantly (p < 0.05) rescued WNV-induced cell death at day 2 after infection ( < 50% when compared to WNV-infected cells)." (PMID 21034511, 2010). "Previous studies of PIC have shown elevated levels of proinflammatory cytokines, such as TNF-α, during the course of infection of guinea pigs." (PMID 19814828, 2009). "At 4 days post-infection German Landrace cells produced significantly more TNF-α than Pietrain cells and Large White cells more than Pietrain and Hampshire cells." (PMID 19383119, 2009). "Anti-TNF-α antibody can reduce mortality of mice during antibiotic-induced TNF-α release during infection, providing a proof for the lethal effects of TNF-α." (PMID 19686585, 2009). "Transfer of apoptotic C. pneumoniae infected PMN to macrophages resulted in an increased TGF-ß production, whereas direct infection of macrophages with chlamydiae was characterized by an enhanced TNF-α response." (PMID 19547701, 2009).
infection (continued). "In response to WT infection, however, there was a strong induction of IL-6 by day 2 post-infection, which preceded the induction of IL-17 and TNF-α, consistent with the established role of IL-6 in Th17 induction." (PMID 19759900, 2009). "The down-regulatory effects of phages on the levels of pro-inflammatory cytokines (particularly TNF-α) during bacterial infection, are in contrast to apparently harmful, increased production of TNF-α during infection induced by antibiotics." (PMID 19686585, 2009). "It has been demonstrated that the levels of expression of many cytokines, including TNFα, TNFγ, IL-6, IL-17 increase dramatically in intestinal lymphocytes during primary infection to E. tenella or E. acervulina." (PMID 19154572, 2009). "In lung tissue from TLR2−/− mice, bacteria were detected as early as day 1, but TNF expression was just barely detectable by day 5 post-infection." (PMID 19936231, 2009). "The initial reasoning for this was that mast cell activation by bacteria led to the secretion of tumor necrosis factor (TNF), recruiting neutrophils to the site of infection." (PMID 23283207, 2009). "Like TNF, it appears that these enzymes are also involved in the necessary recruitment of neutrophils to the site of infection." (PMID 23283207, 2009). "Here, we have demonstrated that TNF-α expression was significantly up-regulated as early as 3 h post-infection in response to H5N1 compared to H1N1 infection." (PMID 20011590, 2009). "Taken together with the data presented in this report, this suggests that the TLR3-dependent production TNF-α plays a particularly important role in cardiac protection following infection with cardiotropic viruses." (PMID 19122812, 2009). "TNFα is a multifunctional hormone-like polypeptide and modulates many genes involved in inflammation, infection, and malignancy." (PMID 20003221, 2009). "The serum levels of TNF-α, IL-1β and IL-6 augmented after challenge, reaching the maximum values between 24 h and 48 h post-infection." (PMID 19835595, 2009). "Infection of monocyte-derived macrophages (MDMs) with HIV-1 also induces TNF-α secretion resulting in a positive autocrine loop that enhances virus production." (PMID 19468304, 2009). "As can be seen, the secretion of TNF-α was elevated after infection with the lysX mutant compared to the wild type and complemented strains, similar to MDMO cells exposed to PMA." (PMID 19649276, 2009). "We observed that upon infection with live S. Typhi, human DC produced high levels of pro-inflammatory cytokines IL-6, IL-8 and TNF-α, but low levels of IL-12 p70 and IFN-γ." (PMID 19517022, 2009). "High levels of IL-1β and TNF-α have also been reported to be released from in vitro explant model upon infection with CT serovar E." (PMID 19698128, 2009). "IL-6 and TNFα were previously known to play an important role in controlling the rapid dissemination of the bacteria upon infection." (PMID 19806192, 2009). "IL-6KO mice treated with rIL-6 during the early immune response following CB3/LPS infection had significantly decreased serum levels of TNF-α, IL-10, MCP-1, MIP-1β, MIG and RANTES as well as decreases in MIP-1α." (PMID 19587788, 2009). "Further, this suggests that TNF-α production is critical to the early immune response following infection." (PMID 19122812, 2009). "We next quantified the inflammatory response by determining IFN-γ and TNF-α titers in lungs of wildtype and cIAP-1 KO mice in response to infection." (PMID 19657383, 2009). "Levels of TNF-α in the cell supernatants varied among the individuals and increased significantly from pre- to both post-infection times when cell samples from German Landrace pigs were used." (PMID 19383119, 2009). "Previous studies showed that TNFRp55−/− and IFN-γR−/− mice are highly susceptible to infection with Ye indicating that the pleiotropic effects of IFN-γ and TNF-α are crucial for the defense against yersiniae." (PMID 19680448, 2009).
infection (continued). "Here, we have demonstrated that levels of TNF and IL-6 and the transcription and DNA binding of NF-κB is significantly and differentially regulated by infection by two distinct MTb strains, HN878 or CDC1551." (PMID 19568431, 2009). "The supernatants were collected at different time points after infection and tested for secreted IL-1β and TNF by ELISA." (PMID 19851467, 2009). "At 21 days post-infection the cells harvested from Hampshire pigs displayed significantly elevated levels of TNF-α in comparison with Pietrain cells." (PMID 19383119, 2009). "We observed a significant reduction of TNF-α release from MF after uptake of C. pneumoniae- infected apoptotic PMN as compared to direct infection with C. pneumoniae (p = 0.01)." (PMID 19547701, 2009). "Previous studies show PIC infection of murine macrophages leads to NF-κB activation, and the production of TNF-α and IL-6." (PMID 19814828, 2009). "Primary macrophages from MyD88−/− and TLR2−/− mice were significantly impaired in the ability to secrete TNF and other pro-inflammatory cytokines upon ex vivo infection with LVS." (PMID 19936231, 2009). "We conclude that histone H3 modification-independent IL-10 induction is not sensitive to suppression by T. gondii, but that histone H3 modification-dependent IL-10 synthesis, like control of TNF-α, is blocked by infection." (PMID 19859561, 2009). "We report here that upon infection with live S. Typhi, human DC produced high levels of pro-inflammatory cytokines IL-6, IL-8 and TNF-α, but low levels of IL-12 p70 and IFN-γ." (PMID 19517022, 2009). "In murine models of malaria, the early production of IL-12, IL-18, TNF and IFN-γ has been associated with the resolution of blood-stage infection." (PMID 19508725, 2009). "As with other APP, infection can increase the production of AGP through cytokines TNF α, IL-1 and IL-6." (PMID 20042096, 2009). "Median time between anti–TNF-α agent start date and infection diagnosis was available for only 68 (65%) of the patients." (PMID 19861045, 2009). "Various uncommon infections such as listeriosis, disseminated histoplasmosis, and other deep fungal infections are reported among patients treated with anti-TNF agents." (PMID 20101303, 2009). "Baseline TNF-α levels in the Wiffle ball fluids of all rabbits were below the lower limit of detection (200 pg/ml) prior to infection." (PMID 19838303, 2009). "We therefore explored the mechanism leading to alteration of TNF-α bioactivity upon infection with the carriage isolate." (PMID 19412525, 2009). "CD8+ Tc1 cells produce cytokines such as IFN-γ and TNF-α that are critical in prevention or control of infection." (PMID 19402893, 2009). "We did a short-term stimulation of unseparated PBMC taken before infection or at day 14 post infection with 3M-007 and determined expression of TNF-α by flow cytometry, gating on CD123+ pDC." (PMID 19424421, 2009). "TNF-alpha levels on day 4 and in moribund animals were significantly lower than on day 11 post-infection (p < 0.001, Bonferroni corrected)." (PMID 19250545, 2009). "On the contrary, serum levels of proinflammatory cytokines were similar in both groups, except for TNF-α production which was significantly higher in IL-4−/− mice with respect to controls (52 ± 10 versus 11 ± 5 pg/mL of serum) at day 2 after infection." (PMID 19606256, 2009). "To this effect, we observed that although MyD88 mice present with reduced immune cell activation following CB4 infection, they produce similar levels of TNF-α and CCL5 compared to WT mice." (PMID 19122812, 2009). "Infection leads to the expression of inflammatory cytokines such as TNF-α, IL-1, and IL-6 as well as other factors such as FasL, heat shock proteins, reactive oxygen species, and nitric oxide, all of which are known to regulate caspase activation." (PMID 20069051, 2009).
infection (continued). "By days 14 and 20, TNF-α gene expression in response to WT infection was reduced to 5-7-fold above those of control and ΔPT groups, indicating an extended response to WT infection similar to that seen for IL-17." (PMID 19759900, 2009). "After 3 h of infection, bacteria were killed with antibiotics and TNF-α was added at 100 ng/ml for 1 h to stimulate RPS3 nuclear translocation." (PMID 20041225, 2009). "Elevated levels of the cytokine TNFα, are found in pregnancies complicated by infection and preterm labour and in normal labour in humans and other species." (PMID 19133144, 2009). "Infection of macrophages with the protozoan parasite Toxoplasma gondii results in inhibition of a large panel of LPS-responsive cytokines, including TNF-α, while leaving others such as IL-10 intact." (PMID 19859561, 2009). "Treatment of THP-1 cells with U0126 totally inhibited the vMyxM013-KO virus-induced secretion of TNF, starting from early times of infection." (PMID 19851467, 2009). "At day 2 after infection significantly higher levels were evident only with regard to TNF-α production, but at the other time points assessed differences became statistically significant also for IL-6 and IL-1β production." (PMID 19606256, 2009). "For both the BALB/c and C57Bl/6 primary lung epithelial cells, TNFα production peaked at 6 h post infection and declined gradually at 24 h and 48 h post infection." (PMID 19806192, 2009). "The higher peak of the pro-inflammatory cytokines detected in elderly animals correlate with reports indicating that elderly populations have enhanced basal levels of these cytokines (e.g. TNF-α) and tendency to produce higher levels upon infection." (PMID 19922665, 2009). "During the early phase of infection, Chlamydia induce anti-apoptotic pathways conferring resistance of the infected host cells to apoptotic stimuli like TNF-α, cycloheximide, staurosporine, FasL, UV and gamma irradiation." (PMID 19657383, 2009). "The amounts of TNF-α produced by cells from Pietrain and Hampshire pigs were significantly higher than those produced by German Landrace cells at pre-infection." (PMID 19383119, 2009). "Naive mice challenged with pRBCs or sporozoites showed a similar induction of IFN-γ, TNF-α, and IL-10 in the serum by 120 hr post blood-stage infection." (PMID 19154991, 2009). "We analyzed the levels of IL-2, IL-4, IL-5, IL-10, IL-12(p70), GM-CSF, IFN-γ and TNF-α in the culture supernatant of macrophages 24 h post infection." (PMID 19680450, 2009). "INF-γ, IL-1, TNF-α and IL-6 are also instrumental in mounting an effective inflammatory response against infection." (PMID 19401694, 2009). "IL-6 together with IL-1 and tumor necrosis factor-α (TNF-α) are some of the major proinflammatory cytokines produced in monocytes and other cells as an immediate response to infection and other stimuli." (PMID 19327150, 2009). "The two neutrophil chemoattractant proteins MIP-2 and KC are induced by both TNF-α and IL-1β in response to inflammatory stimuli such as silica or infection." (PMID 19901996, 2009). "After challenge with the pathogen, these cytokines increased significantly, reaching a peak between 8 h and 12 h post-infection with higher values of TNF-α and IL-6 in the L. casei group." (PMID 19835595, 2009). "In mouse models and in cell lines, the PB1-F2 protein can influence viral pathogenicity, by sensitizing host cells to apoptotic stimuli (e.g. TNFα), thereby promoting apoptosis during infection." (PMID 21994553, 2009). "ELISA results showed that IL-12/23 p40 and TNF-α production in plasma from IL-10−/− mice was higher than wild-type mice plasma samples on day 2 after infection." (PMID 19816558, 2009). "For individuals receiving two to three the times the recommended dose of the TNF-alpha blocking agent, there was a twofold increase in serious infection." (PMID 20016776, 2009). "The current thinking is that mast cell activation leads to the rapid release of TNF and other factors that blunt infection." (PMID 23283207, 2009).